FN1 (fibronectin 1)
Diseases named in the same sentence as FN1 in open-access papers (continued):
Sharing a sentence is not in itself a finding about the gene and the disease.
osteosarcoma (continued). "Our findings revealed the common oncogenic genes such as FN1, COL1A1, and COL1A2, which may act as antioncogene by enhancing cisplatin sensitivity in osteosarcoma cells, and pathways were both in osteosarcoma and Ewing's sarcoma." (PMID 35578666, 2022). "Furthermore, CEP55 was shown to activate CCND1 and FN1 via the AKT signaling pathway, thereby regulating the proliferation and invasion of osteosarcoma cells." (PMID 32149111, 2020). "Our GO enrichment analysis results showed that FN1, COL1A2, and COL1A1 were significantly enriched in the extracellular matrix, protease binding, and so on, indicating that the three genes could play a critical role in the development of osteosarcoma and Ewing's sarcoma." (PMID 35578666, 2022).
colon carcinoma (28 papers, 2003 to 2025). "In conclusion, we demonstrate that highly expressed FN1 is associate with colon cancer metastasis and poor prognosis." (PMID 40638546, 2025). "FN1 assembly has been suggested as a new hallmark of CAFs that promote tumor invasion as indicated in colon cancer-derived CAFs, where CAF contractility induces FN1 assembly and tumor cell invasion." (PMID 33731188, 2021). "Yet, the underlying mechanism of FN1 in colon cancer metastasis was largely unknown." (PMID 40638546, 2025). "To further deeply investigate the detailed mechanism by which FN1 regulates RAP1B in colon cancer, we detected the expression of Akt/CREB signalling pathway." (PMID 40638546, 2025). "FN1 enhanced colon cancer cell migration, invasion, and epithelial to mesenchymal transition (EMT) in vitro and promoted liver and lung metastasis of colon cancer in nude mice through RAP1B." (PMID 40638546, 2025). "In the present study, we demonstrated that FN1 was highly expressed in the primary and metastatic colon cancer and positively related to the poor prognosis of colon cancer." (PMID 40638546, 2025). "Overall, these results suggest that highly expressed FN1 is closely related to the metastasis of colon cancer and correlates with poor prognosis in colon cancer." (PMID 40638546, 2025). "Taken together, this data demonstrates that FN1 can promote colon cancer metastasis in vivo via RAP1B." (PMID 40638546, 2025). "The immunohistochemical result showed that FN1 was mainly located expressed in primary and metastasis colon cancer tissues compared to adjacent normal tissues, which was consistent with the western blot assay." (PMID 40638546, 2025). "In this study, we investigated the role of fibronectin 1 (FN1) in facilitating colon cancer metastasis." (PMID 40638546, 2025). "Next, we performed loss‐of‐function and gain‐of‐function experiments to further investigate the functional effects of FN1 in colon cancer cells." (PMID 40638546, 2025). "Our study provides strong support that the vital role of FN1/RAP1B/CREB loop during colon cancer metastasis." (PMID 40638546, 2025). "Firstly, the mechanism of FN1 promoting colon cancer metastasis was investigated mainly in cell lines, animal models, and several clinical samples, lacking a large scale of clinical research validation." (PMID 40638546, 2025). "A previous study found that FN1 was involved in IRE1α regulated metastatic potential of colon cancer cells." (PMID 40638546, 2025). "For instance, FN1 splicing, which we found to be controlled by CIT in CaP has been associated with colon cancer and splicing of its extracellular domain proposed as therapeutic strategy." (PMID 38658776, 2024). "The expression of ECM proteins such as Fibronectin 1 (FN1) and collagen type 1 α 1 (COL1A1) have been implicated in promoting migration and invasion in colon cancer." (PMID 34885111, 2021). "XBP1 was recently reported to initiate FN1 expression in colon cancer cells and thus deserves further study as a possible link between hypoxia, UPR, and ECM remodeling in the context of EVT differentiation." (PMID 34540826, 2021). "It was found that FN1 was also important in colon cancer proliferation and progression." (PMID 40638546, 2025). "FN1 promotes colon cancer migration, invasion, EMT and metastasis though RAP1B." (PMID 40638546, 2025). "Then we identified that FN1 promoted colon cancer migration, invasion and EMT in vitro." (PMID 40638546, 2025). "Overall, our results elucidated that FN1 promotes colon cancer migration, invasion, and metastasis." (PMID 40638546, 2025). "Taken together, our results reveal that targeting FN1/RAP1B/CREB‐mediated tumour interactions might be an attractive therapeutic strategy for metastasis colon cancer patients." (PMID 40638546, 2025). "FN1 was found to be dysregulated in multiple human cancers, including colon cancer." (PMID 31850052, 2019).
colon carcinoma (continued). "A significant overlap was detected with several relevant gene families, including colon cancer progression (e.g., FN1, IGBP3, PLAUR and TIMP1; P=0.00052), tumour cell apoptosis (e.g., BID, TNFRSF21, PHLDA1 and NOTCH1; P=1.46 × 10–6) and cell proliferation (e.g., CTGF, SPP1, FOLR1 and SPARC)." (PMID 21119668, 2010). "We also assessed whether FN1 mediated colon cancer EMT via RAP1B." (PMID 40638546, 2025). "Furthermore, we validated the expression of FN1 in 3 paired of colon cancer tissues." (PMID 40638546, 2025). "FN1 may be used as the potential therapeutic target for colon cancer metastasis." (PMID 40638546, 2025). "FN1 could regulate colon cancer migration, invasion, EMT, and metastasis by regulating RAP1B." (PMID 40638546, 2025). "In this work, we performed RNA‐seq and observed that FN1 and TIMP1 were the most upregulated genes between metastasis and primary colon cancer tissues as well as between primary colon cancer tissues and adjacent normal tissues." (PMID 40638546, 2025). "Prior studies found that HMGA1 regulates mesenchymal genes in colon cancer cells, such as Vimentin (VIM), N-cadherin (CDH2), E-cadherin (CDH1), and Fibronectin (FN1)." (PMID 34572547, 2021). "The AS of CALD1, COL6A3, FN1, MAST2, LGR5 and ITGB4 were previously validated in colon cancer using RT-PCR24, while CLSTN1, AUP1, CTNND1, CALD1 and COL6A3 were shown to exhibit tumour-specific splice variants in colon, bladder and prostate cancers." (PMID 28592875, 2017). "Although some studies have shown that FN1 modulates several cancers malignant progression including colon cancer, the specific mechanism of FN1 regulating the migration, invasion, EMT and metastasis of colon cancer remains poorly understood." (PMID 40638546, 2025). "Interestingly, CREB was also involved in the induction of FN1 and TIMP1 expression, thereby leading to a positive feedback loop in colon cancer metastasis." (PMID 40638546, 2025). "Finally, we also detected the expression of FN1, TIMP1, and RAP1B in ex vivo by establishing the patient‐derived tumour‐like cell clusters (PTCs) from primary and metastatic colon cancer tumour tissues." (PMID 40638546, 2025). "To further investigate whether FN1 regulates colon cancer migration and metastasis in vitro through RAP1B, we introduced RAP1B shRNAs in FN1‐overexpression HCT116 cells, and transfected FN1‐knockdown LOVO cells with RAP1B overexpression plasmid." (PMID 40638546, 2025). "Furthermore, fibronectin 1 (FN1) has been shown to facilitate the migration and invasion of various cancers, including papillary thyroid cancer, colon cancer, and clear cell renal cell carcinoma." (PMID 38239853, 2023). "Curiously, FN1 and TGFB1 are upregulated by 5-fluorouracil in colon carcinoma cells." (PMID 32824266, 2020).
endometriosis (28 papers, 2011 to 2026). The growth of functional endometrial tissue in anatomic sites outside the uterine body. "With respect to endometriosis, a large meta-analysis combining 11 genome-wide association studies demonstrated that the FN1 gene, encoding Fn, is associated with moderate to severe endometriosis." (PMID 38340184, 2024). "In our omics results, we observed an elevation in the expression of critical fibrosis-associated proteins, including TGFBR1, α-SMA, CTHRC1, FAP, FN1, and 15 collagen proteins, in endometriosis." (PMID 38735939, 2024). "The genetic variant of FN1 rs1250248 was also found to be significantly associated with endometriosis." (PMID 37607964, 2023). "The MGP+ stromal cell subcluster expresses many genes that are associated with the extracellular matrix, including FN1 (encoding fibronectin-1) which has been associated with an increased risk for endometriosis in GWAS studies." (PMID 36104692, 2022). "This subset expresses numerous extracellular matrix genes that have been associated with presence of perivascular stromal cells, senescence, and cell adhesion/cell spreading, including FN1 (which encodes fibronectin-1), a known risk locus for endometriosis." (PMID 36104692, 2022). "This study robustly associated the FN1 locus with endometriosis, in particular with moderate-to-severe disease." (PMID 28537267, 2017). "GWAS and replication analyses have shown that the association between genetic variants in FN1, encoding for fibronectin, and endometriosis is limited to Stage B disease." (PMID 28333195, 2017). "The haplotype and LD studies of the FN1 gene revealed that the identified variations rs6707530 and rs1250248 may both cause TB, and endometriosis respectively." (PMID 37607964, 2023). "Of the previously reported variants associated with endometriosis, most had the directionally concordant effect except for rs1250241, chr2:g.216 295312 T > A at 2q35, FN1, rs517875, chr3:g.174350886 C > A at 3q13, RAP1BP2, and rs13271465, chr8:g.17282411 T > C at 8p22, MTMR7/ADAM24P." (PMID 31488892, 2020). "Five additional new loci significantly associated with the risk of endometriosis (p < 5 × 10−8) of genes involved in sexual steroid hormone pathways (FN1, CCDC170, ESR1, SYNE1 and FSHB) were identified, for a total of 16 genomic regions associated with endometriosis risk in one or more populations." (PMID 32143537, 2020). "In addition to replicating previously reported loci, we identify five novel loci significantly associated with endometriosis risk (P<5 × 10−8), implicating genes involved in sex steroid hormone pathways (FN1, CCDC170, ESR1, SYNE1 and FSHB)." (PMID 28537267, 2017). "Notably, the top genes associated with Stage B endometriosis in these pathways include FN1, FGG and FGA which are also part of the Reactome integrin linkage to MAPK pathways associated with all endometriosis." (PMID 28333195, 2017). "In addition to the six loci, two showed borderline genome-wide significant associations with Stage III/IV endometriosis, including rs1250248 in FN1 (P = 8 × 10−8) and rs4141819 on 2p14 (P = 9.2 × 10−8)." (PMID 24676469, 2014). "The ‘Grade B' fixed-effect meta-analysis implicated rs1250241 in FN1 on 2q35 (OR (95% CI)=1.23 (1.15–1.30); PGrade B=2.99 × 10−9) and rs74491657 on 7p12.3 (OR (95% CI)=1.46 (1.28–1.59); PGrade B=2.24 × 10−8) as genome-wide significantly associated with endometriosis risk." (PMID 28537267, 2017). "In addition to replicating 9 of the 11 previously reported European risk loci, this GWA meta-analysis identified 5 novel loci significantly associated with endometriosis risk (P<5 × 10−8), implicating genes involved in sex steroid hormone pathways (FN1, CCDC170, ESR1, SYNE1 and FSHB)." (PMID 28537267, 2017).
endometriosis (continued). "Increased levels of fibronectin 1 (FN1) by peritoneal macrophages in patients with endometriosis may contribute to the adhesion formation and associated reactive fibrosis seen in this disease and may influence the implantation of endometrial cells and their subsequent growth in the pelvis." (PMID 22203846, 2011). "Further studies are warranted to elucidate the complex fibroblast-immune interactions and to validate FN1-targeted interventions for improved management of endometriosis." (PMID 41159025, 2025). "Of these, FN1 was the most clearly differentiated among mesothelial cells in the three types of endometriosis, both in terms of average cellular expression and in terms of expression analysis at the level of individual cells." (PMID 39968688, 2025). "Results from the current study provide genome-wide evidence for the FN1 locus in Grade B endometriosis, thereby highlighting the importance of subgroup analysis and phenotype definition." (PMID 28537267, 2017). "For the FN1 2q35 and 7p12.3 loci, we used summary statistics from meta-analysis including Grade B endometriosis cases." (PMID 28537267, 2017). "An independent set of 305 laparoscopically proven endometriosis patients and 2710 controls confirmed WNT4, CDKN2BAS, and FN1 as the first identified common loci for endometriosis." (PMID 25722978, 2015). "Similarly, we surmise that endometriosis‐associated mesothelial cells, which experience different EMT process and express different FN1, induced different progesterone resistance of endometrial stromal cells via the FN1‐PI3K‐AKT pathway." (PMID 39968688, 2025). "Based on previous studies and our comprehensive multi-omics analysis, we propose that FN1 plays a key role in the fibrotic process of endometriosis, which regulates the inflammatory response through key fiber cell subsets and through interaction with immune cells." (PMID 41159025, 2025). "The results revealed that knockdown of TRIM33 significantly enhanced the protein expression of TGFBR1/p-SMAD2/α-SMA/FN1, suggesting that the reduced levels of TRIM33 protein in ectopic tissues may exacerbate endometriosis-associated fibrosis." (PMID 38735939, 2024). "However, the interaction mechanism between FN1 and immune cells in endometriosis needs further study." (PMID 35303800, 2022). "Our findings suggest a potential use of GRN and FN1 as clinical biomarkers to detect endometriosis." (PMID 33029756, 2020). "The top 5 genes were the following: EGFR, EZH2, VEGFA, JUN, and FN1 with a degree >15; thus, they might be regulated by miR-200b-3p and play important roles in the progression of endometriosis." (PMID 32802844, 2020). "Notably, this includes FN1, FGG and FGA, which are also part of the Reactome MAPK-related pathways associated with all endometriosis." (PMID 28333195, 2017). "The FN1 region has been associated with many other traits in GWASs; however, none of these SNPs are in LD with endometriosis SNP rs1250248." (PMID 24676469, 2014). "The proposed mechanism involving the FN1‐AKT pathway could serve as a basis for the development of targeted therapies to overcome progesterone resistance in endometriosis, which means that we can target the mesothelium to fix endometriotic progesterone resistance." (PMID 39968688, 2025). "Consequently, we hypothesize that reduced TRIM33 expression in endometriotic tissues may contribute to the development of endometriosis fibrosis by enhancing TGFBR1/p-SMAD2/α-SMA/FN1 expression." (PMID 38735939, 2024). "We conducted a GWA meta-analysis of ∼7 million SNPs in 17,045 endometriosis cases and 191,596 controls, confirmed 9 out of 11 previously reported European risk loci, and identified five new genomic regions in or near CCDC170, SYNE1, FSHB, FN1 and 7p12.3 harbouring endometriosis risk loci." (PMID 28537267, 2017).
endometriosis (continued). "The correlation of aDCs with CXCL8 was the highest, suggesting that FN1 and CXCL8 (IL-8) may promote the infiltration of immune cells and change the local immune microenvironment during the development of endometriosis." (PMID 35303800, 2022). "On the other hand, aberrant activation of some genes (e.g., FN1) and certain enzymes, such as NADPH oxidase, superoxide dismutase and glutathione peroxidase, are important players in inflammation-related diseases, including endometriosis." (PMID 34768846, 2021). "The correlation index of FN1 vs. five kinds of immune cells was greater than 0.5 and the correlation coefficient between aDCs and CXCL8 was the highest, indicating a close interplay between the immune/inflammatory response and endometriosis development and progression." (PMID 35303800, 2022). "Moreover, cyto-hub gene analysis revealed that CSNK2A1, CSNK2A2, TOP1, PRKACA, RBM39 (plasma), ALB, ACTB, GAPDH, FN1, APOA1 (serum), S100-A9, CXCL1, IL1RN, CSTA, S100-A8 (menstrual blood) and THBS1, ALB, CD44, ANXA2, and LUM (urine) were the top 5 proteins expressed in women with endometriosis." (PMID 39061077, 2024).
breast tumor (25 papers, 2006 to 2025). "The glycoprotein fibronectin 1 serves as a hallmark of CAFs and has been indicated as a facilitator of breast tumor stroma remodeling, for instance by promoting CAFs-mediated migration and invasion of tumor cells." (PMID 38937754, 2024). "Three downregulated markers, PEA15, PRDX4, and FN1, also showed low protein expression in breast tumors, as confirmed with immunohistochemistry staining." (PMID 37128318, 2023). "Using GEPIA, RET and FN1 levels were found to be significantly higher in breast tumor tissues than in normal tissues." (PMID 36601474, 2022). "We used Oncomine to investigate the expressions of COL1A1 and FN1 in human breast tumor invasion and metastasis." (PMID 30237810, 2018). "Of note, the roles of COL1A1 and FN1 related to breast tumor invasion are still unclear." (PMID 30237810, 2018). "Next, the prognostic value of FN1, PLAU and ALCAM was evaluated in a microarray data set of breast tumors from 2878 patients." (PMID 34641959, 2021). "CDH1 and ELF3 were expressed at a significantly higher level in cells with an epithelial morphology, whereas FN1, FOSL1, VIM, ZFHX1B, SNAI2, SERPINE1 and TFGB1 showed a higher expression in fibroblastic breast tumour cells." (PMID 16495925, 2006). "However, downregulated secretome markers FN1, PSMB6, PRDX4, and PEA15 are also upregulated at the mRNA level in breast tumors." (PMID 37128318, 2023). "Another downregulated secretome marker, FN1, showed no staining in breast tumor tissue, while normal tissues showed low-intensity staining." (PMID 37128318, 2023).